MEG3 (maternally expressed 3)
Diseases named in the same sentence as MEG3 in open-access papers (continued):
Sharing a sentence is not in itself a finding about the gene and the disease.
tumor (continued). "Knockdown of MEG3 abolished the activation effect of DDP on NLRP3/caspase-1/GSDMD pathway-mediated pyroptosis, and reversed the suppression of DDP on tumor growth and metastasis ability in vitro and in vivo." (PMID 34326697, 2021). "On the other hand, a number of so-called tumor suppressor lncRNAs namely CASS2 and MEG3 are down-regulated in HCC." (PMID 33968749, 2021). "To summarize, GAS5, MEG3, LINC0111, and LINC00261 are tumor-suppressors in PDAC that act via inhibition of EMT." (PMID 34820419, 2021). "Therefore, it is possible to speculate on a downmodulation of Meg3 by the expressed KSHV miRNAs as an early event in the viral cycle followed by an upmodulation of Meg3 as a response of the host cell to the already triggered tumor growth." (PMID 34222014, 2021). "Instead, low expressions of several tumor suppressor lncRNAs namely PSTAR, CASC2, lnc-FTX, LINC00472, TSLNC8, miR503HG, MEG3, LIN00607, AOC4P, uc.134, GAS8-AS1, LINC00657, MAGI2-AS3, LINC01093, GAS5, SchLAH, and NKILA predict patients’ outcome." (PMID 33968749, 2021). "In this study, we found that MEG3 expression was significantly downregulated in HCC tissues, and this was closely related to tumor development, invasion, and metastasis." (PMID 34895065, 2021). "Thereafter, in order to assess the effect of MEG3 on tumor cell proliferation and clonogenic capability, we transfected HEY and PEO1 cells (HGSOC cell lines) with pMEG3 (MEG3 expression plasmid) to transiently over-express the transcript." (PMID 32295169, 2020). "Downregulated MEG3 can regulate cell proliferation, EMT, and apoptosis in NSCLC tumor tissues from patients with an advanced pathological stage, as well as in cell lines." (PMID 32438606, 2020). "MEG3 sponges miR-421, further regulating the growth factor PDGFRA and activating the Notch pathway to induce tumor growth and angiogenesis." (PMID 32992718, 2020). "In EC, it was demonstrated that lncRNA MEG3 can be directly combined with PI3K, thus impacting tumor growth." (PMID 31947591, 2020). "In CC tissues, MEG3 is downregulated, compared to the adjacent normal tissues, and it is negatively related to FIGO stages, tumor size, HR-HPV infection, lymphatic metastasis and expression of miR-21." (PMID 33371204, 2020). "In contrast, lncRNA MEG3 was down-regulated in NSCLC, and MEG3 overexpression inhibits the growth of tumor." (PMID 32975291, 2020). "We previously demonstrated that maternally expressed 3 (MEG3)-derived miR-493-5p tumor-suppressor was epigenetically silenced by CpG hypermethylation in HCC cells and tumor tissues from patients." (PMID 33937011, 2020). "More specifically, MEG3, MCF2L-AS1, LINC00483, and TP73-AS1 were downregulated in CRC tumor tissues compared to NATs." (PMID 33552987, 2020). "In general, this present study revealed that MEG3 was down-regulated in MEN tissues and cells, serving as a tumor-suppressive lncRNA in MEN malignancy." (PMID 33251130, 2020). "Tumor suppressive lncRNAs (GAS5, MEG3, FER1L4 and LINC00672) and oncogenic lncRNAs (CCAT2, BANCR, NEAT1, MALAT1, H19 and Linc-RoR) have been identified as key regulators of the established tumor suppressor or oncogenic pathways in EC." (PMID 30781521, 2019). "Then we examined the level of P-STAT3 protein in the tumor tissues in the tumor formation experiment and found that the expression of P-STAT3 protein was significantly decreased in MEG3 group." (PMID 31320837, 2019). "High expression levels of lncRNA HEGBC, PAGBC, PVT1 and UCA1 predicted high tumor node metastasis (TNM) stages, while lncRNA LET, GCASPC and MEG3 indicated low TNM stages." (PMID 31297033, 2019). "Actually, numerous lncRNAs function as oncogenes or tumor-suppressor genes, which were reported to be involved in metastasis and prognosis of HCC, such as MEG3, GAS5, HOTAIR, HULC, H19, and MALAT1." (PMID 31500187, 2019).
tumor (continued). "Maternally Expressed 3 (MEG3) is an imprinted lncRNA which is expressed in many different cell types and tissues and acts as a tumor suppressor and is downregulated in many types of cancer." (PMID 31212604, 2019). "Either high expression of HOTTIP, LINC00152, LINC00673, MALAT1 and UCA1, or low expression of AC007392.4, MEG3 and NKILA is found in tumor tissues." (PMID 29416703, 2018). "When taking into account the different tumour subtypes, we detected 24 SNPs (in eight genes: ZDBF2, PEG10, MEST, H19, IGF2, MEG3, ZNF331 and HM13) exhibiting DI in at least one subtype compared to the normal tissue samples." (PMID 30297886, 2018). "Tumor suppressors including KiSS1, BRCA1, p16, MEG3 and PPAR-gamma are known to inhibit the tumor cell migration and invasion." (PMID 28584306, 2017). "In order to explore the potential role of circulating cell-free lncRNAs as the biomarkers for the diagnosis of BC, we first analyzed the correlation of MEG3, SNHG16 and MALAT1 expression levels between 36 serum samples and corresponding tumor tissue samples." (PMID 27793008, 2016). "Recently, several lncRNAs have been found to play an emerging role in various cancers, contributing to tumor proliferation, apoptosis, and survival, such as PANDAR, MEG3." (PMID 27514530, 2016). "MEG3, HOXA13, and KCNQ1OT1 were all overexpressed in HCC tumor tissues (P = 0.001, P < 0.001, and P = 0.004, resp)." (PMID 26136615, 2015). "To identify MEG3 that is altered in expression in HCC, we detected the expression levels of MEG3 in 23 pairs of HCC tissues and adjacent non-tumor tissues." (PMID 26444285, 2015). "We found 5 of these CARs/lincRNAs (MALAT1, MEG3, NEAT1, NBPF1, and AC058791.1) significantly downregulated in primary tumor samples compared to normal tissue." (PMID 25264628, 2014). "In cancer, expression of tumour suppressor lncRNAs, such as GAS5 or MEG3, should decrease tumour growth." (PMID 23887658, 2013). "Several genes displayed correlations between epigenetic modification and clinically relevant parameters, including invasiveness (CDKN2A; DAPK; Rb1), sex (MAGE-A3), tumor size (GNAS1), and histopathological subtype (CDKN2A; MEG3; p27; RASSF1A; Rb1)." (PMID 24367530, 2013). "The aim of this study was to examine the expression pattern of MEG3 in NSCLC and to evaluate its biological role and clinical significance in tumor progression." (PMID 24098911, 2013). "Interestingly, the analysis revealed that Meg3, MIAT and SNHG20 are primarily expressed by cells localized at the tumor edge or infiltrating the tumor core." (PMID 40527978, 2025). "Likewise, CAF-derived exosomal lncRNA maternally expressed 3 (MEG3) binds miR-15a-5p in small cell lung cancer (SCLC) cells, derepressing cyclin E1 (CCNE1) to drive cisplatin chemoresistance and tumor progression." (PMID 41409273, 2025).
tumor (continued). "Additionally, NBAT1 functions as a tumor suppressor in RCC, inhibiting proliferation, migration, and invasion, aligning with MEG3’s effects and serving as a prognostic biomarker." (PMID 40242248, 2025). "Multiple lncRNAs regulate VEGF expression in tumor cells under various conditions, including Testis Development-Related Gene 1 (TDRG1), MEG3, H19, SNHG1, Non-Coding RNA Activated by DNA Damage (NORAD), Antisense Non-Coding RNA in the INK4 locus (ANRIL), and MALAT1." (PMID 40429961, 2025). "In the context of cancer, the frequent downregulation of MEG3 and overexpression of TDRG1 may synergistically enhance VEGF-driven vascular remodeling, facilitating immune escape and tumor dissemination." (PMID 40429961, 2025). "Among other tumour-suppressive lncRNAs, GAS5 stands out as most similar to MEG3." (PMID 40242248, 2025). "Because GNAS mutations are speculated to participate in upregulating MEG3 expression, the expression levels of MEG3 in NFPA and GHPA tumor tissues were quantified via RT-qPCR." (PMID 38827318, 2024). "The results indicated the tumor suppressor roles of PTENP1, GNG12-AS1, MEG3 and MAGI2-AS3." (PMID 38277283, 2024). "The reasons for different than expected results for HOTIAR, MEG3 and TUG1 (family) are unknown, but the different material analyzed (tumor tissue vs serum) should be taken into account." (PMID 38601651, 2024). "The results illustrated that MEG3 was dramatically downregulated in tumor tissues compared with non-tumor tissues." (PMID 38047026, 2023). "Regarding MEG3, a recognized tumor suppressor, it inhibits tumor progression in breast cancer mainly by suppressing AKT signaling and also inhibits capillary angiogenesis in endothelial cells by reducing the expression of tumor angiogenic factors." (PMID 37602326, 2023). "A lower expression level of MEG3 is seen in OSCC tumour tissues than is seen in non-malignant tissues, and it is associated with OSCC progression and a high OSCC mortality rate." (PMID 36428681, 2022). "In the current study, a significantly lower expression of MEG3 was observed in GC tissues as compared to adjacent non-tumor tissues which is in consistent with the tumor suppressor function of this lncRNA." (PMID 35186192, 2022). "MEG3, a tumor-suppressive lncRNA, was significantly down-regulated in Cd-transformed BEAS-2B cells likely due to the increased methylation of the differentially methylated region (DMR) upstream of the MEG3 transcription start site by induction of DNMTs." (PMID 36497250, 2022). "Furthermore, MEG3 expression levels in somatotroph tumors were positively correlated with patient serum GH and IGF1 levels and conversely negatively correlated with tumor size." (PMID 36010855, 2022). "Although many tumor-suppressing lncRNAs are under investigation, the most documented are the growth arrest-specific transcript 5 (GAS5), the maternally expressed gene 3 (MEG3), and the NF-kB interacting lncRNA (NKILA)." (PMID 35978835, 2022).
tumor (continued). "Although the functions of MEG3 were diversiform in nontumor disease, the tumor suppressor effect of MEG3 was concerned widely." (PMID 35898889, 2022). "Treatment of PDFS cells with RGFP966 restored expression of MEG3, a long non-coding RNA tumor suppressor, whose expression is lost in NFPAs but not in hormone secreting pituitary adenomas." (PMID 35646715, 2022). "The results showed that MEG3 and HOTAIR expression levels could discriminate tumor from non-tumor tissues with specificities 86% and 74%, and sensitivities 79% and 84% respectively." (PMID 35186192, 2022). "In addition, tumor proliferation marker MKI67 was also reduced, and the expression of caspase-3 increased in the lncRNA MEG3 group." (PMID 36005145, 2022). "Among genes significantly downregulated by MEG3 knockdown, as determined by a −2 fold-change from MEG3-knockdown to control, were MMP-1, MMP-9, and MMP-16, three metalloproteases with previously characterized roles in tumor metastasis." (PMID 36231143, 2022). "Consistent with findings from other studies, our experiments supported a tumour suppressor role of MEG3, showing a negative correlation between MEG3 expression and development of NB in vitro." (PMID 35257481, 2022). "On the contrary, several tumor suppressor lncRNAs, namely CASS2 and MEG3, are downregulated in HCC." (PMID 36005145, 2022). "MEG3 directly targets the proto-oncogene c-MET (hepatocyte growth factor receptor) to block cell proliferation and delay cell cycle progression, and it also displays an anti-tumor effect through manipulating the p38/ERK/Akt and Wnt/β-catenin pathway in a MEG3/miR183/BRI3 dependent manner." (PMID 36248960, 2022). "Together, these results show a negative correlation between MEG3 and tumor progression as well as prognosis, indicating the potential of using MEG3 as a biomarker for tumor prognosis." (PMID 36551518, 2022). "MEG3 acts as ceRNA for a number of miRNAs; its sponging of miR-9-5p derepresses QKI-5 expression to inhibit cell proliferation, migration, invasion and in vivo xenograft tumour growth in Pca." (PMID 35159022, 2022). "On the contrary, Rictor down-regulated MEG3 and GAS5, both of which are tumor suppressive lncRNAs." (PMID 34540654, 2021). "Along with MEG3, maternally expressed non-protein-coding RNA 9 encoded by MEG9 gene, plays a protective role in tumor angiogenesis in response to DNA damage." (PMID 33572862, 2021). "Moreover, the authors reported that MEG3 levels were positively correlated with GH and IGF1 serum levels, whilst they were negatively correlated with tumor size." (PMID 34484116, 2021). "Additionally, MEG3 overexpression inhibited HCC tumorigenesis and progression in xenograft tumor models while depletion of MEG3 exerted the opposite way." (PMID 34895065, 2021). "It was observed that POU3F3 and MEG3 were significantly and inversely correlated across tumor tissues but not normal tissues." (PMID 35201451, 2021). "The patient population enrolled in this study was, however, very small (only 21 patients), so that no definitive conclusion on the role of MEG3 in tumor pathogenesis can be drawn." (PMID 34439223, 2021). "Finally, as reported in methods, we overlapped these lists, in order to obtain a set of potential tumor-suppressor lncRNAs (i.e., DLEU1, LINC00261, LINC00483, LINC01207, MCF2L-AS1) and oncogene lncRNAs (MEG3, RUNX1-IT1, and TP73-AS1) to experimentally analyze." (PMID 33552987, 2020).
tumor (continued). "Overexpression of MEG3 inhibited tumorigenesis in vivo and reduced NSCLC cell proliferation, as well as induced apoptosis in vitro, suggesting that delivery of tumor suppressor lncRNAs such as MEG3 may potentially be an alternative therapeutic option in NSCLC." (PMID 32629922, 2020). "The apoptosis induced by MEG3 was also accompanied by SUC accumulation, indicating a mechanism of tumour suppression by MEG3 might be through SUC accumulation, HIF‐1α activation and apoptosis promotion during the malignant transformation from OLP to OSCC." (PMID 31793175, 2020). "Numerous studies show that MEG3 is expressed in a variety of normal tissues, but not in most tumor tissues or tumor cell lines 16-18." (PMID 33061817, 2020). "Among them, maternally expressed gene 3 (MEG3) has been reported to be aberrantly expressed in CRC and may act as a tumor suppressor." (PMID 32219064, 2020). "Survival analysis of all tumor samples showed reduced, but not significant overall survival in patients with high MEG3 expression." (PMID 32612992, 2020). "MEG3 is a potential tumor suppressor gene in several cancer types, mainly through the observation that MEG3 expression is lower in various tumor tissues compared with non-tumor tissues of the same origin." (PMID 32612992, 2020). "Previous studies have suggested that some lncRNAs may promote tumor progression through the dysregulation of tumor proliferation, apoptosis (e.g., MA-LINC1, HOTAIR), metastasis (e.g., MALAT1), and angiogenesis (e.g., MIAT, MEG3)." (PMID 32083005, 2020). "Tumor suppressive lncRNAs (GAS5, MEG3, FER1L4 and LINC00672) and oncogenic lncRNAs (CCAT2, BANCR, NEAT1, MALAT1, H19, Linc-RoR, TUG1, TDRG1 and PCGEM1) may be a few such examples." (PMID 30781521, 2019). "The direct therapeutic effect of MEG3 on tumor growth in liver cancer and fibrotic liver has not been yet established." (PMID 30158867, 2018). "MEG3 has been proposed as a tumor suppressor and a negative regulator of angiogenesis, and its down-regulation serves as an unfavorable risk factor for survival in multiple human cancer types, mainly by promoter and IG-DMR region hypermethylation." (PMID 30395586, 2018). "Knockdown of LINC00673, MALAT1 and UCA1, and overexpression of MEG3 and NKILA can inhibit tumor progression, which might become prospective treatment methods." (PMID 29416703, 2018). "It is broadly distributed in many normal human tissues; however, MEG3 is not expressed in a series of human tumors and tumor cell lines, such as tongue squamous-cell carcinoma (TSCC), brain cancer, and hepatocellular cancer." (PMID 27802187, 2017). "By therapeutically inducing MEG3 expression in PCA, its tumour-suppressive effects may help to control progress of disease." (PMID 28241429, 2017). "MEG3 expression is much lower in TSCC tumor tissues than in nearby nonmalignant tissues, and patients with low MEG3 expression always have short survival times." (PMID 27802187, 2017). "MEG3, JPX, RNCR3, and ZFAS1 showed significant decrease with tumour malignant progression." (PMID 29138748, 2017). "In addition, Meg3 protected ATG3 mRNA from degradation following treatment with actinomycin D. Overall, our results suggest that the lncRNA Meg3 acts as a tumor suppressor in EOC by regulating ATG3 activity and inducing autophagy." (PMID 28423647, 2017). "It is interesting to note that both HOTAIR and MEG3 bind GA-rich sequence elements that facilitate recruitment of PRC2 complex and condense the local chromatin environment, yet HOTAIR functions as an oncogene while MEG3 functions as a tumor suppressor." (PMID 29113413, 2017).